IFNAR1 (interferon alpha and beta receptor subunit 1)
Diseases named in the same sentence as IFNAR1 in open-access papers (continued):
Sharing a sentence is not in itself a finding about the gene and the disease.
Stroke (6 papers, 2014 to 2023). Sudden impairment of blood flow to a part of the brain due to occlusion or rupture of an artery to the brain. "Type 1 IFN-stimulated genes reaction in the microglia exposed to ischemia/reperfusion depends on innate immune receptors including TLR4 and IFNAR1, which played a deleterious role in the outcome after stroke." (PMID 32746852, 2020). "Furthermore, mice with MG-specific IFNAR1 knockdown were generated to validate the effects of IFNβ on modulating MG phenotypes, ameliorating brain injury, and lessening BBB disruption in delayed tPA-treated stroke animals." (PMID 37063896, 2023). "Thus, it is possible that IFNAR1 signaling induces STAT3 activation, leading to the suppression of tPA-enhanced inflammatory molecules, IL-1α, IL-1β and CD86, expression and the promotion of anti-inflammatory molecules, Arg1 and CD206, upregulation in MG in delayed tPA-treated stroke animals." (PMID 37063896, 2023).
cerebral malaria (5 papers, 2016 to 2022). A sequestration of Plasmodium falciparum in the brain, which can cause coma and/or seizures. "The development of cerebral malaria in children has previously been associated with a variant of IFNAR1 associated with a higher expression of IFNAR1." (PMID 36146602, 2022). "Our present study demonstrates that Ifnar1-/- mice, which lack type I interferon receptor-dependent signaling, are protected from experimental cerebral malaria (ECM) when infected with this novel parasite." (PMID 34659202, 2021).
hepatocellular carcinoma (5 papers, 2014 to 2025). A malignant tumor that arises from hepatocytes. "While this association was observed in human cohorts, TIM1 did not play a role in entry into Huh-7.5 human hepatoma cells and mice lacking IFNAR1/TIM1 or IFNAR1/TIM4 remained susceptible to HAV infection and disease, suggesting TIM1 may play a limited role in HAV-induced disease." (PMID 41020590, 2025).
latent infection (5 papers, 2011 to 2025). "miR-US33as-5p targets interferon alpha and beta receptor subunit 1 (IFNAR1) and confers IFN resistance during both lytic and latent infection." (PMID 35746686, 2022). "Interestingly, chronically infected myeloid U1 and OM10.1 cell lines have reduced IFNAR1 expression, indicating that brain pericytes may respond differentially to HIV latent infection." (PMID 41041557, 2025). "In this study, we observed an increased frequency of latent infection, but not ex vivo reactivation, in peritoneal cells of mice with B cell-specific deficiency of either STAT1 or IFNAR1, implicating B cell-intrinsic type I IFN signaling in the control of the peritoneal latent reservoir." (PMID 39440973, 2024).
liver fibrosis (5 papers, 2010 to 2025). "To evaluate the role of type I IFN signaling in liver fibrosis, cell proliferation and apoptosis associated with liver regeneration defects, we established an IFNAR1 blockade model by administering IFNAR1 antibodies to CCl4-treated mice for three days prior to liver harvest." (PMID 40260261, 2025). "Overall, IFNAR1 blockade enhances anti-inflammatory signaling and cell survival in monocyte-derived macrophages during CCl4-induced liver fibrosis, as evidence by increased M2/M1 ratios and P-STAT3 activation." (PMID 40260261, 2025). "The scRNA-seq analysis underscores the impact of IFNAR1 blockade on gene expression in macrophages from a CCl4-induced liver fibrosis model." (PMID 40260261, 2025). "To determine the role of type I IFN signaling in liver fibrosis, we administered an IFNAR-1 antibody to block this pathway for 3 days prior to harvesting the liver." (PMID 40260261, 2025). "Picrosirius red staining revealed a significant reduction in liver fibrosis in the CCl4+IFNAR1 group compared to the CCl4-only group, both visually and quantitatively." (PMID 40260261, 2025). "Taken together, IFNAR-1 blockade alleviates liver fibrosis progression by modulating macrophage inflammatory responses." (PMID 40260261, 2025). "Overall, analysis of fibrosis severity, cell proliferation, and apoptosis suggests that IFNAR1 blockade alleviates CCl4-induced liver fibrosis by reducing both cell proliferation and apoptosis." (PMID 40260261, 2025). "In this study, we examined the role of macrophage mediators in liver fibrosis using CCl4-treated mice, specifically investigating how IFNAR1 signaling regulates fibrosis." (PMID 40260261, 2025). "Our previous overlapping analysis between the 20 top pathways associated with aggressive disease identified IFNAR1 and SERPINE1 as common genes between the Host-Coronavirus Pathogenesis and the Hepatic Fibrosis/ HSC Activation." (PMID 36672763, 2022). "Notably, IFNAR-1 blockade reduced macrophage numbers compared to control mice and alleviated liver fibrosis in mice with increased hepatocyte proliferation and apoptosis." (PMID 40260261, 2025). "To functionally define the role of IFN-I in liver fibrosis in HIV/cART mice, we treated mice from 7 to 10 wpi with anti–IFNAR1 Ab or an isotype control and euthanized mice at 12–13 wpi." (PMID 35639478, 2022). "Liver fibrosis along with inflammatory changes observed in ABIN1[D485N] mice were drastically reduced after crossing to IRAK4[D329A] or IRAK1[D359A] mice but were not reduced by crossing to IFNAR1-KO mice." (PMID 27807192, 2016).
pneumococcal infection (5 papers, 2013 to 2023). Infections with bacteria of the species streptococcus pneumoniae. "Studies in IFNAR1 or IFN-β knockout mice showed that the abolishment of the IFN-β-IFNAR1 pathway increased nasopharyngeal carriage and enhanced mortality upon pneumococcal infection." (PMID 28848552, 2017). "To elucidate the function of IFN-I during pneumococcal infection, we i.n. challenged Ifnar1−/− and Ifnar1+/+ mice with D39X and followed disease progression." (PMID 24244159, 2013). "Ifnar1−/− mice showed constitutively enhanced permeability of the lung which was significantly increased upon pneumococcal infection in comparison to Ifnar1+/+ mice, the latter of which showed only a modest increase in lung permeability upon infection." (PMID 24244159, 2013). "IFNβ mRNA has been reported to be substantially upregulated upon pneumococcal infection and during pneumococcal carriage and mice lacking IFNAR1 or IFNβ display prolonged nasopharyngeal carriage and enhanced mortality upon pneumococcal infection." (PMID 24244159, 2013).
anemia (4 papers, 2021 to 2024). A reduction in the number of red blood cells, the amount of hemoglobin, and/or the volume of packed red blood cells. "The embryonic anemia in Pich‐KO mice was also partially rescued by Ifnar1 deletion." (PMID 35037428, 2022).
bacteremia (4 papers, 2013 to 2025). "Mice that were treated with anti-IFNAR1 developed bacteremia faster than those that received the isotype control antibody." (PMID 24244159, 2013). "However, in the peripheral blood, pneumococci were detected significantly earlier and at higher numbers in Ifnar1−/− mice compared to Ifnar1+/+ animals, with 45% of the Ifnar1−/− mice exhibiting bacteremia by 18 hours post-challenge compared to 18% of the Ifnar1+/+ animals." (PMID 24244159, 2013). "Intranasal infection models of mice lacking the IFNAR1 or treated with neutralizing antibodies against IFNAR1 showed enhanced development of bacteremia." (PMID 40525851, 2025). "Mice lacking IFNAR1 or mice treated with a IFNAR neutralizing antibody showed an increase in bacteremia." (PMID 33362795, 2020).
Candida infection (4 papers, 2012 to 2021). "To test for in vivo production of IFNs-I upon systemic Candida infections, we infected WT and IFNAR1-deficient mice with Ca by lateral tail vein injection (iv)." (PMID 22911155, 2012).
co-infection (4 papers, 2019 to 2024). "Notably, the increased levels of PEDV replication associated with PoRVA co-infection were similar in IFNAR1-/- and WT IPEC-J2 cells." (PMID 38905309, 2024). "The selective function of IFNβ in our co-infection model is supported by data on its ability to bind to IFNAR1 in an IFNAR2 independent manner activating a unique set of genes in LPS shock." (PMID 31500303, 2019).
dementia (4 papers, 2021 to 2026). Loss of intellectual abilities interfering with an individual's social and occupational functions. "We have previously demonstrated that disruption of the IFNβ-IFNAR1 signalling pathway is associated and can cause development of PD with dementia." (PMID 37779111, 2023). "Accordingly, mice knock-out for Ifnb or Ifnar1 develop Parkinson-like disease with dementia (PDD)." (PMID 37779111, 2023). "Next, we verified selected genes in the type I IFN signature in our patient cohort by RT-qPCR, which confirmed their differential regulation in sPD patients and those with dementia, including IFNA17, IFNB, and IFNAR1." (PMID 34234281, 2021).
Hepatic steatosis (4 papers, 2012 to 2025). Steatosis is a term used to denote lipid accumulation within hepatocytes. "We propose that future studies should be conducted to determine if attenuating the ER-stress response by pharmacological inhibitors or siRNA knockdown improves the antiviral response of IFN-α in the condition of hepatic steatosis by retained expression of IFNAR1." (PMID 22863531, 2012). "Notably, mice knockout of IFN-α/β receptor subunit 1 (IFNAR1)−/− fed on HFD were protected from IR and hepatic steatosis, whereas administration of anti-IFNAR1 antibody in the same mouse model improved glucose tolerance and IR, although body weight did not change." (PMID 40794228, 2025).
Hepatitis B (4 papers, 2014 to 2025). "Other groups have shown association with polymorphisms in IFNAR1 and Hepatitis B and C infection and disease." (PMID 25756647, 2015). "Hepatitis B virus infection induces the production of matrix metalloproteinase 9, which in turn promotes Hepatitis B virus replication by interacting with IFNAR1 and facilitating the degradation of IFNAR1." (PMID 40668839, 2025).
lung disease (4 papers, 2020 to 2022). "Although it has been suggested that IFNAR1 mediates STING-associated autoinflammation, we discovered an unexpected role for IFNGR1 in regulating lung disease and T cell and macrophage dysfunction in SAVI mice that have a STING gain-of-function mutation." (PMID 36073546, 2022). "Although it was hypothesized that STING-associated lung disease would require the type I IFN receptor (IFNAR1), we and others demonstrated that IFNAR1 is dispensable for lung disease in SAVI mice." (PMID 36073546, 2022). "In contrast, deletion of IFNAR1 or IFNλR1s did not ameliorate lung disease or affect T cell and macrophage phenotypes in SAVI animals." (PMID 36073546, 2022). "Our discoveries indicate that STING-associated lung disease and T cell phenotypes are indeed IFN related but unexpectedly mediated by IFNGR1, rather than by IFNAR1 or IFNλR1." (PMID 36073546, 2022).
lymphoma (4 papers, 2020 to 2023). A malignant (clonal) proliferation of B- lymphocytes or T- lymphocytes which involves the lymph nodes, bone marrow and/or extranodal sites. "In summary, miR130b enhanced B-lymphoma cell sensitivity to OX40 agonistic antibody and LNPs miR130b antagomir through modulating OX40/OX40L-mediated lymphoma cell interaction with Th17 cells via IFNAR1/p-STAT1 axis." (PMID 35301282, 2022).
myeloma (4 papers, 2021 to 2023). "Using animal models of multiple myeloma, we found that both the depletion of all FoxP3+ Tregs and the selective ablation of IFNAR1 on Tregs induced tumor remission in an aggressive murine myeloma model." (PMID 38993887, 2023). "Myeloma-cell-secreted type 1 IFN has been suggested as a mediator of Treg activation and expansion in a syngeneic transplantable murine myeloma model, in which treatment with a blocking IFNAR1 antibody inhibited myeloma progression." (PMID 33435306, 2021). "The reason could be that sustained Type I IFN signaling is key for the expansion of LAG3+ Tregs, as it was shown that blocking type I IFNs receptor by IFNAR1 antibody hindered myeloma-driven LAG3+ Treg expansion." (PMID 37833265, 2023).
nephritis (4 papers, 2015 to 2025). Inflammation of renal tissue. "IFN-I exacerbates nephritis progression, and mice deficient in IFNAR1 develop a less severe phenotype upon cGN induction." (PMID 40393992, 2025).
pancreatitis (4 papers, 2014 to 2026). Inflammation of the pancreas. "Pancreas-specific ablation of interferon (alpha and beta) receptor 1 (Ifnar1) partially protected animals from caerulein-induced pancreatitis, as demonstrated by reduced tissue damage." (PMID 26618925, 2015). "Intriguingly, pancreatitis induces many pathways known to downregulate IFNAR1 such as VEGF, unfolded protein response (Kubisch ' Logsdon, 2007), and pathogen recognition receptors." (PMID 24480543, 2014). "Our current data suggest that stimulation of IFNAR1 downregulation during pancreatitis functions as a protective mechanism that limits the extent of tissue damage and promotes the transition of inflammatory process to the stages of tissue regeneration." (PMID 24480543, 2014). "In addition, the pancreatitis-induced increase in blood plasma TNFα levels were also greater in Ifnar1SA (7.89 fold) than in Ifnar1+/+ (4.50-fold) mice." (PMID 24480543, 2014).
periodontitis (4 papers, 2019 to 2025). An acute or chronic inflammatory process that affects the tissues that surround and support the teeth. "Second, we believe that it will be more meaningful to use cGAS-and IFNAR1-deficient mice together to study the impact of P. gingivalis on the pathogenesis of periodontitis." (PMID 37405166, 2023). "In the periodontitis group, macrophages were observed to exhibit elevated expressions of TLR4, IFNAR1 (the receptor of IFNβ), ISG15, ITGB2 (the receptor of ISG15), IL10." (PMID 37876725, 2023). "Significantly elevated Ifnar1 expression was observed in LSK, CMP, GMP, and NeuP populations from LIP mice compared to Ctrl mice, suggesting that IFN-I may act directly on these cell populations by activating IFN-I signaling in these cells to induce skewed neutropoiesis in periodontitis." (PMID 40521205, 2025).
type 1 diabetes (4 papers, 2011 to 2021). "IFNAR1 was downregulated in individuals with new-onset type 1 diabetes and it had an SNP associated with type 1 diabetes." (PMID 33973017, 2021). "Our data provide additional details regarding the IFN-α-signaling pathway during type I diabetes based on the use of antibodies to label proteins downstream of IFNAR1, such as STAT1, STAT2, AKT, and IκB-α." (PMID 23533683, 2013).
chronic hepatitis C (3 papers, 2012 to 2023). "According to the treatment response in the Japanese population, rs2243594 (G allele, IFNAR1) was associated with neutropenia in chronic hepatitis C patients receiving interferon (IFN) plus ribavirin combination therapy." (PMID 38003785, 2023). "IFNAR-1 mRNA levels were measured in PBMC from naïve patients with chronic hepatitis C with different IL-28 genotypes." (PMID 24691098, 2014). "Our results are also supported by a number of studies where the role of IFNAR1 expression has been correlated with the response to IFN-α therapy in chronic hepatitis C." (PMID 22863531, 2012).
Cirrhosis (3 papers, 2012 to 2023). A chronic disorder of the liver in which liver tissue becomes scarred and is partially replaced by regenerative nodules and fibrotic tissue resulting in loss of liver function. "Upregulation of type I (Ifn) encoding genes (Ifna2 and Ifnar1), important in first line defense against microbial invasion and loss of immune tolerance were seen in inflammation and cirrhosis stages compared to all other timepoints (all P < 0.01)." (PMID 33858327, 2021). "Genes involved in cirrhosis development (ABCG2, CTNNB1, B2M, IFNAR1, IFNAR2), and hepatic cholestasis (CYP7B1) were found significantly down-regulated in patients without HCC." (PMID 22792259, 2012).
colon adenocarcinoma (3 papers, 2018 to 2025). "Furthermore, the acquired radiosensitivity of the colon adenocarcinoma IFNAR1 knockout cells depended on the presence of CD8 T effector cells." (PMID 36571986, 2023). "Analysis of TCGA colon adenocarcinoma (COAD) data revealed that STAT2 expression was significantly elevated in tumor tissues compared with normal colon samples (p = 0.00012), a pattern that was also observed for IFNAR1 (p = 0.0046)." (PMID 41440237, 2025).
echovirus infection (3 papers, 2022 to 2026). "To dissect the relative contributions of type I and type III IFNs in protecting the liver during echovirus infection, we combined in vivo mouse models (expressing hFcRn and deficient in Ifnar1, Ifnlr1, or both) with single cell RNA sequencing (scRNA-seq)." (PMID 41592119, 2026).
experimental autoimmune encephalomyelitis (3 papers, 2016 to 2020). An autoimmune demyelinating disease of the central nervous system that is produced experimentally in animals by the injection of homogenized brain or spinal cord in Freund's adjuvant. "Purified IgG2a monoclonal anti-MOG antibody and mouse complement were stereotactically injected into the corpus callosum of wild-type and type I IFN receptor deficient mice (IFNAR1-KO) with and without pre-established experimental autoimmune encephalomyelitis (EAE)." (PMID 28646890, 2017).
herpes simplex encephalitis (3 papers, 2021 to 2023). Herpes simplex virus encephalitis (HSE) is caused by the infection of the central nervous system by Herpes simplex virus (HSV) that could have a devastating clinical course and a potentially fatal outcome particularly with delay or lack of treatment. "Furthermore, probable wild type mumps complicated by sensorineural deafness, as well as Herpes simplex encephalitis, were also described by the same group within a kindred with IFNAR1 deficiency [31••]." (PMID 34107321, 2021).
intestinal infection (3 papers, 2023 to 2025). "Thus, conditional intestinal epithelial Ifnar1−/− mice develop resistance to C. parvum intestinal infection." (PMID 36928642, 2023). "Next, to determine whether the systemic spread of CR6 required initial intestinal infection for subsequent dissemination or could occur independent of the intestine, we analyzed the distribution of barcodes across tissues in WT, Ifnar1-/-, Ifnar1-/-Ifngr1-/-, and Stat1-/- mice." (PMID 38701091, 2024).
neuroblastoma (3 papers, 2013 to 2021). Neuroblastoma (NB) is the most common solid, extracranial childhood tumor. "Furthermore, this study investigates knockdown of IFNAR1 in M17 neuroblastoma cells alone in the context of OGD." (PMID 24602263, 2014). "miRNA appeared to be downregulated in neuroblastoma cell lines due to promoter methylation, but treatments with 5′azacitidine increased miRNA expression and led to malignancy decrease through downregulation of miRNAs’ targets such as CDK6, DNMT3B, E2F3, OLFM3, and IFNAR1." (PMID 34832966, 2021).
ocular infection (3 papers, 2025 to 2026). "Here, we investigated the role of autophagy in ZIKV ocular pathogenesis utilizing a primary human trabecular meshwork cells (HTMC) and IFNAR1-/- mouse model of ocular infection." (PMID 40920489, 2025). "At a dose of 1 × 103 PFU/eye, none of the infected IFNAR1-/- mice survived ocular infection (data not shown), while 100% of infected IFNβ-/- mice survived." (PMID 40353667, 2025).
ovarian carcinoma (3 papers, 2020 to 2022). A malignant neoplasm originating from the surface ovarian epithelium. "Secondly, the survival analyses of patients with ovarian cancer clearly indicated that the expression levels of CALR, PDIA3, ANXA1, HMGB1, IFNAR1, and PANX1 had no significant influence on overall survival (OS) and disease-free survival (DFS)." (PMID 35991556, 2022). "Firstly, the expression analyses of patients with ovarian cancer showed that the expression levels of CALR and PDIA3 in ovarian cancer were significantly up-regulated in compared with normal control tissues, while the expression of PANX1, ANXA1, HMGB1, and IFNAR1 were nonsignificant." (PMID 35991556, 2022).
reovirus infection (3 papers, 2015 to 2017). "Under these experimental conditions, Ifnar1-/- mice developed neurological symptoms and succumbed to reovirus infection within 5–7 days." (PMID 25849543, 2015).